N4BP2 (NEDD4 binding protein 2)
Description:
Has 5'-polynucleotide kinase and nicking endonuclease activity. May play a role in DNA repair or recombination. May play a role in the non-stop mRNA decay pathway (NSD), which specifically targets and degrades mRNAs that lack a proper stop codon.
Synonyms: B3BP
Tractability: Small molecule: it has a high-quality binding pocket. Antibody: the Human Protein Atlas places it where antibodies can reach. PROTAC: UniProt records ubiquitination sites on it; ubiquitination databases record sites on it; its protein half-life has been measured.
Gene: Protein-coding gene on chromosome 4 (40,056,658 to 40,158,252, forward strand). Ensembl gene ENSG00000078177.
Subcellular location: Cytoplasm
Subcellular location (Human Protein Atlas): Nucleoplasm; Cytosol; Plasma membrane
Gene Ontology:
Molecular function: ATP binding; ATP-dependent polydeoxyribonucleotide 5'-hydroxyl-kinase activity; DNA endonuclease activity; endonuclease activity; protein binding; ubiquitin binding
Biological process: nuclear-transcribed mRNA catabolic process, non-stop decay
Cellular component: cytoplasm; cytosol
Genetic constraint (gnomAD): Loss-of-function variants: 67 observed, 108.94 expected, observed/expected ratio (o/e) 0.62, 90% interval 0.5 to 0.75. The upper end of that interval is the gene's LOEUF score, 0.75, which puts it in group 3 of 6, group 1 being the genes least tolerant of losing a copy. Missense variants: 1,608 observed, 1,806.1 expected, observed/expected ratio (o/e) 0.89, 90% interval 0.85 to 0.93. Synonymous variants: 540 observed, 628.18 expected, observed/expected ratio (o/e) 0.86, 90% interval 0.8 to 0.92.
Homologues: Orthologues: chimpanzee N4BP2 (99% identical), macaque N4BP2 (96% identical), dog N4BP2 (82% identical), pig N4BP2 (79% identical), rabbit N4BP2 (76% identical), rat N4bp2 (72% identical), guinea pig N4BP2 (68% identical), mouse N4bp2 (68% identical), tropical clawed frog n4bp2 (34% identical). Paralogues in human: N4BP2L2 (7% identical), N4BP2L1 (5% identical).
Diseases named in the same sentence as N4BP2 in open-access papers:
N4BP2 is named in the same sentence as 7 diseases in open-access papers, as found by Europe PMC text mining. Sharing a sentence is not in itself a finding about the gene and the disease. The quoted sentences say what the papers report.
pulmonary fibrosis (3 papers, 2021 to 2025). Chronic progressive interstitial lung disorder characterized by the replacement of the lung tissue by connective tissue, leading to progressive dyspnea, respiratory failure, or right heart failure. "N4BP2 was reported to be involved in pulmonary fibrosis and nasopharyngeal carcinoma." (PMID 34026864, 2021). "Pulmonary fibrosis showed increased expression of serine/threonine-protein kinase PLK2 (Q9NYY3) and NEDD4-binding protein 2 (Q86UW6), while alveolar infiltrates exhibited reduced expression of protein WWC3 (Q9ULE0), Rho-associated protein kinase 1 (Q13464), and apolipoprotein A-IV (P06727)." (PMID 41279897, 2025).
cleft lip (1 paper, 2024). Congenital defect in the upper lip where the maxillary prominence fails to merge with the merged medial nasal prominences. "Variants of N4BP2 may be associated with nonsyndromic cleft lip in humans." (PMID 39350025, 2024).
schizophrenia (1 paper, 2017). A major psychotic disorder characterized by abnormalities in the perception or expression of reality. "The network analysis of the 7 annotated genes revealed 5 networks, each with PARK2, N4BP2, KCNIP4, ADGRL2, or NCOA7 as its focus gene, which may have joint influence on the initiation of schizophrenia." (PMID 28744025, 2017).
cancer (3 papers, 2007 to 2025). A tumor composed of atypical neoplastic, often pleomorphic cells that invade other tissues. "N4BP2 is a Bcl-3 binding protein, and Bcl-3 is an oncoprotein that is overexpressed in certain cancers, including NPC." (PMID 17626640, 2007). "We also found that N4BP2 and Bcl-3 are expressed in all NPC cell lines examined and were higher for certain cancers." (PMID 17626640, 2007).
tumor (2 papers, 2007 to 2025). "N4BP2 is implicated in fibrotic processes and angiogenesis, potentially influencing tumor microenvironments." (PMID 40136480, 2025). "Moreover, N4BP2 was at higher levels in a majority of tumor tissues examined, relative to paired normal tissues." (PMID 17626640, 2007). "N4BP2 and Bcl-3 mRNA levels appeared to be higher in tumor than in matched normal tissue." (PMID 17626640, 2007).
N4BP2 also shares sentences with these, for which no sentence is quoted: nasopharyngeal carcinoma (2 papers); lung carcinoma (1).